TEKTL1 (tektin like 1)
Description:
Microtubule inner protein (MIP) part of the dynein-decorated doublet microtubules (DMTs) in sperm flagellar axoneme, which is required for motile flagellum beating (By similarity). Forms an extensive interaction network cross-linking the lumen of axonemal doublet microtubules (By similarity).
Synonyms: CCDC105; FLJ40365
Tractability: No criterion of Open Targets' tractability assessment is met for any kind of drug.
Gene: Protein-coding gene on chromosome 19 (15,010,726 to 15,023,276, forward strand). Ensembl gene ENSG00000160994.
Subcellular location: Cytoplasm, cytoskeleton, flagellum axoneme
Gene Ontology:
Molecular function: protein binding
Biological process: flagellated sperm motility
Cellular component: extracellular exosome; axonemal B tubule inner sheath; sperm flagellum; cilium; cytoplasm
Genetic constraint (gnomAD): Loss-of-function variants: 40 observed, 37.18 expected, observed/expected ratio (o/e) 1.08, 90% interval 0.83 to 1.4. The upper end of that interval is the gene's LOEUF score, 1.4, which puts it in group 5 of 6, group 1 being the genes least tolerant of losing a copy. Missense variants: 765 observed, 630.04 expected, observed/expected ratio (o/e) 1.21, 90% interval 1.14 to 1.29. Synonymous variants: 297 observed, 260.11 expected, observed/expected ratio (o/e) 1.14, 90% interval 1.04 to 1.26.
Homologues: Orthologues: chimpanzee CCDC105 (99% identical), macaque TEKTL1 (95% identical), dog TEKTL1 (83% identical), pig TEKTL1 (81% identical), mouse Tektl1 (79% identical), rat Tektl1 (78% identical), rabbit TEKTL1 (71% identical), guinea pig TEKTL1 (62% identical).
Diseases named in the same sentence as TEKTL1 in open-access papers:
TEKTL1 is named in the same sentence as 1 disease in open-access papers, as found by Europe PMC text mining. Sharing a sentence is not in itself a finding about the gene and the disease.
TEKTL1 shares sentences with these, for which no sentence is quoted: asthenozoospermia (1 paper).